PATL2 (PAT1 homolog 2)
Description:
RNA-binding protein that acts as a translational repressor.
Synonyms: Pat1a; hPat1a; OOMD4; OZEMA4
Tractability: PROTAC: ubiquitination databases record sites on it.
Gene: Protein-coding gene on chromosome 15 (44,665,732 to 44,711,370, reverse strand). Ensembl gene ENSG00000229474.
Subcellular location: Cytoplasm; Nucleus
Gene Ontology:
Molecular function: protein binding; RNA binding
Biological process: negative regulation of translation; P-body assembly; deadenylation-dependent decapping of nuclear-transcribed mRNA
Cellular component: cytoplasm; nucleus; ribonucleoprotein complex; P-body
Genetic constraint (gnomAD): Loss-of-function variants: 70 observed, 73.44 expected, observed/expected ratio (o/e) 0.95, 90% interval 0.79 to 1.16. The upper end of that interval is the gene's LOEUF score, 1.16, which puts it in group 5 of 6, group 1 being the genes least tolerant of losing a copy. Missense variants: 596 observed, 645.57 expected, observed/expected ratio (o/e) 0.92, 90% interval 0.86 to 0.99. Synonymous variants: 256 observed, 253.96 expected, observed/expected ratio (o/e) 1.01, 90% interval 0.91 to 1.12.
Homologues: Orthologues: chimpanzee PATL2 (99% identical), macaque PATL2 (96% identical), dog PATL2 (83% identical), pig PATL2 (80% identical), rabbit PATL2 (79% identical), rat Patl2 (72% identical), guinea pig PATL2 (71% identical), mouse Patl2 (68% identical), tropical clawed frog patl2 (46% identical), zebrafish patl2 (38% identical), Drosophila melanogaster Patr-1 (21% identical), Caenorhabditis elegans patr-1 (19% identical). Paralogues in human: PATL1 (34% identical).
Diseases named in the same sentence as PATL2 in open-access papers:
PATL2 is named in the same sentence as 18 diseases in open-access papers, as found by Europe PMC text mining. Sharing a sentence is not in itself a finding about the gene and the disease. The quoted sentences say what the papers report.
female infertility (9 papers, 2021 to 2025). Diminished or absent ability of a female to achieve conception. "Our findings provide more insights into the significant impacts of both novel and recurrent PATL2 variants on female infertility and failed assisted reproduction." (PMID 40657385, 2025). "This study expands the spectrum of PATL2 variants and provides pathogenic evidence for genetic counseling for female infertility." (PMID 39741299, 2024). "Previous studies have reported mutations in PATL2 those led to female infertility with oocyte maturation arrest; however, the mechanisms by which mutations affected meiotic maturation remained unclear." (PMID 33614659, 2021). "PATL2 deficiency is a significant cause of female infertility." (PMID 40704065, 2025). "PATL2 mutations have mainly been associated with oocyte maturation and female infertility." (PMID 37040172, 2023). "Previous studies have reported that variants in PATL2 lead to female infertility with oocyte maturation arrest; however, the mechanisms by which PATL2 variants affect meiotic maturation remain unclear and controversial." (PMID 36072676, 2022). "In mice, Patl2 knockout leads to oocyte maturation arrest, characterized by morphological and developmental abnormalities in both oocytes and zygotes, ultimately resulting in female infertility." (PMID 40657385, 2025). "Since CDC23 is a key protein for oocyte cell cycle progression and the biallelic mutations in CDC23 cause human OMD and female infertility, we determined whether CDC23 is a downstream effector of PATL2 in cell cycle regulation." (PMID 39741299, 2024). "Our findings establish the causal relationship between PATL2 and the phenotype of multi-phenotype in human, which may provide new understanding of PATL2 for female infertility." (PMID 39741299, 2024). "Moreover, variants in PATL2 (MIM: 614661; NM_001145112.2) can also cause female infertility." (PMID 36072676, 2022). "In this study, we designed a target-sequencing panel with 22 female infertility-related genes, namely, TUBB8, PATL2, WEE2, and PANX1 and sequenced 68 primary infertility (PI) and recurrent pregnancy loss (RPL) patients." (PMID 35620457, 2022).
Infertility (8 papers, 2018 to 2025). "In humans, biallelic PATL2 variants, including homozygous or compound heterozygous variants lead to infertility due to oocyte germinal vesicle (GV) arrest or MI arrest, fertilization failure, and early embryo developmental arrest." (PMID 40704065, 2025). "Homozygous or compound heterozygous variants in PATL2 lead to infertility due to oocyte arrest at the germinal vesicle (GV) or metaphase I (MI) stage, fertilization failure, and early embryonic developmental arrest." (PMID 39684710, 2024). "Pat1-Homolog-2 (PATL2) regulates transcription and translation during oogenesis, and loss of PATL2 leads to infertility in women due to oocyte maturation arrest." (PMID 38764035, 2024). "In a study by Liu, R., PATL2 mutations were investigated in 40 patients with infertility due to oocyte maturation arrest." (PMID 39684710, 2024). "In summary, we identified three novel mutations in PATL2 gene in infertile patients exhibiting OMD, expanding the genotype spectrum of OMD." (PMID 39741299, 2024). "In conclusion, our study identified several novel and recurrent mutations in PATL2 of primary infertile female and emphasized its pathogenicity and phenotypic consistency." (PMID 33614659, 2021). "PATL2 plays a major role in oocyte maturation while mutations are linked with infertility both in women and mice." (PMID 34361119, 2021). "In this study, we identified seven different missense mutations including four novel mutations and three recurrent mutations in PATL2 from five sporadic primary infertile cases and one family with two infertile sisters." (PMID 33614659, 2021). "After bioinformatics analysis based on our filtering protocols (see section Materials and Methods), we identified mutations in PATL2 which may be responsible for the phenotypes of these infertile females." (PMID 33614659, 2021). "Since the orthologue of PATL2 in Xenopus is described as an important factor in Xenopus oocyte maturation, it was possible that this variant could be the cause of these subjects’ infertility." (PMID 29661911, 2018). "In this study, three novel pathogenic variants in PATL2 are identified in infertile women exhibiting recurrent OMD in first part, and we validate the pathogenic effects of mutations on PATL2 protein and its function." (PMID 39741299, 2024). "Our work expands the understanding of the pathogenesis of PATL2 gene mutations and recommends a rationally advanced IVM method in combination with PATL2 target gene diagnosis for infertile patients affected by oocyte maturation arrest." (PMID 33614659, 2021). "Another significant member of the spectrum of genes responsible for the infertility profiles is Phosphoinositide-Binding Protein (PATL2) which has been correlated with oocyte maturation arrest, fertilization failure, and embryonic developmental arrest." (PMID 34361119, 2021). "In addition to the studies from China that identified WEE2 mutations as a genetic basis for infertility, TFF has also been associated with mutations in PATL2." (PMID 32667031, 2020). "Since our PATL2 patients exhibited normal hormone levels (when data were available) and reported regular menstrual cycles, these results taken together suggest that the human infertility phenotype is purely due to an oocyte defect." (PMID 29661911, 2018).
asthma (1 paper, 2023). "However, a study that looked at whole-genome expression found PATL2 to be differentially expressed in obese and normal weight individuals with asthma compared to controls." (PMID 37040172, 2023).
polycystic ovary (1 paper, 2023). "The expression of PATL2 in granulosa cells of polycystic ovary patients was reported to have significantly increased." (PMID 37255713, 2023).
synucleinopathies (1 paper, 2024). "Further studies are needed to determine if PATL2 has any involvement with other neurodegenerative conditions, especially those that involve synucleinopathies." (PMID 38719867, 2024).
neurodegenerative disease (2 papers, 2020 to 2024). A disorder of the central nervous system characterized by gradual and progressive loss of neural tissue and neurologic function. "PATL2, however, remains a poorly studied gene especially within the neurodegenerative diseases." (PMID 38719867, 2024).
PATL2 also shares sentences with these, for which no sentence is quoted: amyotrophic lateral sclerosis (2 papers); neuroblastoma (2); Alzheimer disease (1); aneuploidy (1); Arthritis (1); COVID-19 (1); depression (1); Huntington disease (1); infection (1); myeloma (1); Parkinson disease (1); progressive supranuclear palsy (1).